MRPS11 (mitochondrial ribosomal protein S11)
Synonyms: MRP-S11; S11mt; HCC-2; FLJ23406; FLJ22512; uS11m
Tractability: Small molecule: a structure with a bound ligand is known. PROTAC: ubiquitination databases record sites on it; its protein half-life has been measured.
Gene: Protein-coding gene on chromosome 15 (88,467,421 to 88,480,776, forward strand). Ensembl gene ENSG00000181991.
Subcellular location: Mitochondrion
Subcellular location (Human Protein Atlas): Mitochondria
Pathways (Reactome):
Metabolism of proteins: Mitochondrial ribosome-associated quality control; Mitochondrial translation elongation; Mitochondrial translation initiation; Mitochondrial translation termination
Gene Ontology:
Molecular function: protein binding; RNA binding; structural constituent of ribosome
Biological process: mitochondrial translation; translation
Cellular component: mitochondrial small ribosomal subunit; mitochondrion; mitochondrial inner membrane; ribosome
Genetic constraint (gnomAD): Loss-of-function variants: 25 observed, 22.74 expected, observed/expected ratio (o/e) 1.1, 90% interval 0.8 to 1.53. The upper end of that interval is the gene's LOEUF score, 1.53, which puts it in group 6 of 6, group 1 being the genes least tolerant of losing a copy. Missense variants: 267 observed, 259.1 expected, observed/expected ratio (o/e) 1.03, 90% interval 0.93 to 1.14. Synonymous variants: 103 observed, 100.22 expected, observed/expected ratio (o/e) 1.03, 90% interval 0.88 to 1.21.
Homologues: Orthologues: chimpanzee MRPS11 (99% identical), macaque MRPS11 (89% identical), pig MRPS11 (78% identical), dog MRPS11 (76% identical), guinea pig MRPS11 (76% identical), rat Mrps11 (74% identical), rabbit MRPS11 (73% identical), mouse Mrps11 (71% identical), tropical clawed frog mrps11 (56% identical), zebrafish mrps11 (52% identical), Caenorhabditis elegans mrps-11 (35% identical), Drosophila melanogaster mRpS11 (35% identical). Paralogues in human: RPS14 (23% identical).
Diseases named in the same sentence as MRPS11 in open-access papers:
MRPS11 is named in the same sentence as 13 diseases in open-access papers, as found by Europe PMC text mining. Sharing a sentence is not in itself a finding about the gene and the disease. The quoted sentences say what the papers report.
ischemic stroke (3 papers, 2023 to 2025). A stroke disorder caused by obstruction of blood flow to the brain, due to thrombotic (local blood clot formation) or embolic (due to a blood clot or other material traveling from another site) event. "It has been shown that MRPS11 shows significant downregulation in the peripheral blood of ischemic stroke patients." (PMID 39290696, 2024). "Furthermore, MRPS11 expression is significantly downregulated in the peripheral blood of patients with ischemic stroke, where it serves as an important biomarker for assessing prognostic risk." (PMID 41013856, 2025). "Additionally, MRPS11 and MRPS12 could potentially serve as therapeutic targets for the treatment of ischemic stroke, as mitochondrial dysfunction has been implicated in stroke pathophysiology." (PMID 37418282, 2023). "The present study identified MRPS11 and MRPS12 as robust markers in transcriptomic analysis of ischemic stroke." (PMID 37418282, 2023). "One potential application of MRPS11 and MRPS12 is as biomarkers for the diagnosis of ischemic stroke." (PMID 37418282, 2023). "At last, PCR showed that MRPS11 and MRPS12 were significantly down-regulated in peripheral blood of patients with ischemic stroke." (PMID 37418282, 2023). "We found that both MRPS11 and MRPS12 were down-regulated in ischemic stroke patients in the GSE16561 and GSE58294 data sets (p < 0.001)." (PMID 37418282, 2023). "Further research is needed to validate the robustness of MRPS11 and MRPS12 as markers for ischemic stroke diagnosis and as therapeutic targets." (PMID 37418282, 2023). "MRPS11 and MRPS12 have the potential to serve as biomarkers for ischemic stroke diagnosis, either alone or in combination with other biomarkers." (PMID 37418282, 2023). "The results showed that compared with healthy controls, MRPS11 and MRPS12 were significantly down-regulated in peripheral blood of patients with ischemic stroke (**P < 0.01, ***P < 0.001)." (PMID 37418282, 2023). "Protein-protein interaction network analysis revealed that MRPS11 and MRPS12 were key genes, both of which were down-regulated in ischemic stroke." (PMID 37418282, 2023). "The identification of MRPS11 and MRPS12 as potential markers in transcriptomic analysis of ischemic stroke highlights the importance of these genes in neurological disorders and their potential as therapeutic targets." (PMID 37418282, 2023). "Finally, in order to verify the expression of MRPS11 and MRPS12 in peripheral blood of patients with ischemic stroke, clinical samples were collected and PCR experiments were conducted." (PMID 37418282, 2023).
depression (2 papers, 2023 to 2025). "Given the role of mitochondrial dysfunction in the pathophysiology of depression, MRPS11 and SHMT2 may represent potential therapeutic targets for this condition." (PMID 41013856, 2025). "In summary, the potential role of MRPS11 and SHMT2 in depression, through mitochondrial dysfunction and oxidative stress, offers new insights into the pathogenic mechanisms and potential therapeutic strategies for MDD." (PMID 41013856, 2025).
ovarian carcinoma (2 papers, 2023 to 2025). A malignant neoplasm originating from the surface ovarian epithelium. "Recent studies have shown that the interaction between LncRNA ZFHX4-AS1 and MRPS11 may be closely associated with the immune microenvironment in ovarian cancer, thereby promoting its progression." (PMID 41013856, 2025). "A study found that the interaction between LncRNA ZFHX4-AS1 and MRPS11 may be related to the immune microenvironment in ovarian cancer and promote ovarian cancer progression." (PMID 37418282, 2023).
uveal melanoma (2 papers, 2020 to 2023). A melanoma derived from melanocytes of the uveal tract. "MRPS11 appeared to be a robust prognostic indicator in uveal melanoma; up-regulated MRPS11 was associated with worse overall survival." (PMID 37177979, 2023). "Through a bioinformatics analysis such as gene ontology, MRPS11 was found to be overexpressed in uveal melanoma and is a potential prognostic indicator for uveal melanoma." (PMID 33238645, 2020).
ankylosing spondylitis (1 paper, 2025). An autoimmune chronic inflammatory disorder characterized by inflammation in the vertebral joints of the spine and sacroiliac joints. "In patients with ankylosing spondylitis (AS), MRPS11 expression is also notably reduced, suggesting its involvement in the disease’s pathobiological mechanisms." (PMID 41013856, 2025).
chronic obstructive pulmonary disease (1 paper, 2025). A chronic and progressive lung disorder characterized by the loss of elasticity of the bronchial tree and the air sacs, destruction of the air sacs wall, thickening of the bronchial wall, and mucous accumulation in the bronchial tree. "Additionally, MRPS11 has been implicated in the pathogenesis of chronic obstructive pulmonary disease (COPD)." (PMID 41013856, 2025).
Parkinson disease (1 paper, 2025). A progressive degenerative disorder of the central nervous system characterized by loss of dopamine producing neurons in the substantia nigra and the presence of Lewy bodies in the substantia nigra and locus coeruleus. "GSEA revealed significant co-enrichment of MRPS11 and SHMT2 in pathways related to the “ribosome,” “Parkinson’s disease,” and “olfactory transduction”." (PMID 41013856, 2025).
cancer (2 papers, 2023 to 2025). A tumor composed of atypical neoplastic, often pleomorphic cells that invade other tissues. "In particular, MRPS11 and MRPS12 have been implicated in the pathogenesis of cancer." (PMID 37418282, 2023). "Notably, MRPS11 has been identified as a potential contributor to cancer pathogenesis." (PMID 41013856, 2025).
infection (1 paper, 2021). The state of being infected such as from the introduction of a foreign agent such as serum, vaccine, antigenic substance or organism. "Upon infection, the expression of mRpS11, RpL23, and RpL27 was significantly upregulated in midgut 1 dpi or fat body 7 dpi." (PMID 34061577, 2021).
mitochondrial disease (1 paper, 2022). "Mitochondrial disease-causing mutations were found in thirteen small ribosomal subunit mitoribosomal proteins (MRPS1, MRPS2, MRPS6, MRPS7, MRPS9, MRPS11, MRPS14, MRPS16; MRPS22, MRPS23, MRPS25, MRPS34, MRPS39) and four large ribosomal mitochondrial proteins (MRPL3, MRPL12, MRPL24, MRPL44)." (PMID 36140315, 2022).
MRPS11 also shares sentences with these, for which no sentence is quoted: tumor (2 papers); neurological disorders (1); Stroke (1).